MMP9 (matrix metallopeptidase 9)
Diseases named in the same sentence as MMP9 in open-access papers (continued):
Sharing a sentence is not in itself a finding about the gene and the disease.
tumor (continued). "This vascularization facilitates the metastatic process, promoting the migration/circulation of tumor cells, thanks to matrix degradation by matrix metalloproteinases (MMP2, MMP7 and MMP9), which are released by tumor cells and by TAMs as well." (PMID 27823976, 2016). "MMP-9 activity promotes the infiltration of inflammatory cells into various tissues, and it is reported to mediate the VEGF-induced vascular invasion of tumor cells." (PMID 26839315, 2016). "Among various MMPs, MMP-9 and MMP-2 play crucial roles in tumor cell metastasis and invasion by degradation of type IV collagen, a major component of the ECM." (PMID 26968952, 2016). "MDSCs function in immune suppression and secrete several pro-tumor factors such as nitric oxide (NO), reactive oxygen species (ROS), vascular endothelial growth factor (VEGF), and matrix metalloproteinase 9 (MMP9), all of which contribute to tumor progression." (PMID 27996037, 2016). "Matrix metalloproteinase 9 (MMP-9), which is important in tumor invasion and metastasis through degrading extracellular matrix, is up-reulated by AEG-1 partly through NF-κB p65 in macrophages." (PMID 27793010, 2016). "MMP-2 and MMP-9, two of the main proteolytic enzymes for degrading the extracellular matrix (ECM) and the basement membrane, are known to be critical for tumor metastasis." (PMID 27329841, 2016). "The Matrix Metalloproteinase 9 (MMP-9), a proteolytic enzyme that degrades the extra-cellular matrix components, is involved in tumor invasion and metastatic dissemination." (PMID 27387327, 2016). "Recently, IL-6 has been found to promote tumor invasion and angiogenesis, in addition to proliferation and survival, but through upregulation or activation of MMP2 and MMP9." (PMID 27613828, 2016). "Metalloproteinase-9 (MMP-9) belongs to a family of proteolytic enzymes that catalyze extracellular matrix (ECM) degradation and has a critical role in several stages of tumor progression." (PMID 27578191, 2016). "It showed FA-CD-PLLD/DOC/MMP-9 nanocomposite had a good targeting ability to achieve the high DOC concentration and gene transfection efficiency in HNE-1 tumor." (PMID 27259274, 2016). "Reduction in MMP2 and MMP9 expression after S100A8 and S100A9 knockdown in the cancer cells suggests their regulation by the S100 proteins, and is consistent with decreased tumor cell migration and invasion." (PMID 27086923, 2016). "Conversely, TIS-CD8+ T cells promote CD16+ expression in monocytes/macrophages and the production of pro-inflammatory cytokines (TNF, IL-1β, and IL-6) and angiogenic factors (MMP-9, VEGF-A, and IL-8), which can affect tumor progression." (PMID 27129159, 2016). "In tumor microenvironment, tumor cells can degrade and remodel the ECM by excessively secreting matrix MMPs such as MMP-2 and MMP-9." (PMID 27042656, 2016). "To understand the potential mechanisms of Pol ι-mediated tumor invasion and metastasis, we examined the effect of altered Pol ι levels on MMP-2 and MMP-9 expression in our model systems." (PMID 27057634, 2016). "MMP-9 plays an important role in tumor angiogenesis by modulating the bioavailability of vascular endothelial growth factor (VEGF), a tumor angiogenesis marker and a promising therapeutic target." (PMID 26998758, 2016). "The role of TAMs in tumor neovascularization is thought to involve a wide array of pro-angiogenic factors and enzymes, including VEGF-A, VEGF-C, and MMP9." (PMID 27029067, 2016). "We also investigated the role of miR-875-5p on expression of MMP-7 and MMP-9, which all play a key role on tumor metastasis, and results indicated miR-875-5p inhibited the protein expression of MMP-7 and MMP-9 both in HCT116 and SW480 cells." (PMID 27302926, 2016). "Tumor exosomes contain multiple angiogenesis-related proteins, such as angiogenin, HGF, MMP-9, serpin E1, tissue inhibitor of metallopeptidase-1, thrombospondin 1 and VEGF, that promote ECs growth and angiogenesis." (PMID 27474171, 2016).
tumor (continued). "Here, we reported that significantly higher levels of matrix metallopeptidase 9 (MMP9), and significantly lower levels of miR-3713 were detected in TCC tissue, compared to the adjacent non-tumor tissue, and were inversely correlated." (PMID 27577949, 2016). "Active NFκB upregulates the expression of genes such as VEGF-C, iNOS, MMP-9, ICAM-1 and VCAM-1that regulate tumor angiogenesis and promote tumor metastasis." (PMID 27314329, 2016). "Here, we elucidated the tumor progressive effects of EMP3 through PI3K/Akt pathway and uPA/MMP-9 cascade in HCC cells." (PMID 26472188, 2015). "It has been previously shown that IL-12 also regulates the levels of MMP-9 and TIMP-1 in the tumor micro-environment of BC model." (PMID 27275301, 2015). "Given that MMPs and EMT were involved in tumor cells metastasis, we further investigated the link between HDAC4 expression and E-cadherin, Vimentin, MMP2 and MMP9 expression." (PMID 26441331, 2015). "Since MMP9 and MMP2 regulate tumor microenvironment and tumor metastasis, in theory, the invasion and metastasis of tumor can be inhibited through decreasing the activity of MMP9 and MMP2." (PMID 26674531, 2015). "AR, MMP-2 and MMP-9 expression levels in HCC tissues have the potential to be employed as predictors of the progression of local cancer invasion and the tumor stage." (PMID 25667651, 2015). "It was previously shown that IL-12 regulates MMP9 and TIMP1 in the tumor micro enviroment leading to reduced MMP9 and increased TIMP1 levels in IL-12 treated tumors." (PMID 27275301, 2015). "It was found that inhibition of IL-17 at tumor sites significantly suppressed CD31+, MMP9 and VEGF expression in tumor tissue." (PMID 25590298, 2015). "EO771.LMB expressed higher levels of MMP-9 and MMP-3 that have been shown to facilitate tumour cell invasion." (PMID 25633981, 2015). "Recently, many tumor markers such as SCCA, CEA, CA19-9, MMP-9, IL-6, CYFRA 21–1, DKK-1, M-CSF, MiR-18a, MiR-1246 and many other genes were evaluated for ESCC diagnosis." (PMID 25608466, 2015). "MMP9 is treated as a “general commander” of ECM remodeling, in charge of the final degrading of collagenous fiber, releasing tumor cells from the surrounding complicated network." (PMID 26674531, 2015). "NF-κB plays a critical role in the regulation of proteins involved in the cell survival (Bcl-2, XIAP), proliferation (cyclin-D1), invasion (MMP-9, RANKL), angiogenesis (VEGF), and inflammation (COX-2, TNF-α), all contribute to the tumor progression." (PMID 26487364, 2015). "The expression rates of AR, MMP-2 and MMP-9 in the HCC tissue were 76.67, 73.33 and 76.67%, respectively, all of which were significantly higher than those in the tissues adjacent to the tumor." (PMID 25667651, 2015). "Zymogel analysis of MMP2 and MMP9 gelatinase activity showed that, while MMP9 is weakly expressed in all cells tested, MMP2 expression in extracellular medium varies between tumour cell lines." (PMID 26284589, 2015). "It was found that the expression of MMP-3 in MSI-L/MSS CRC tumours was greater than in MSI-H tumours, in which the levels of active MMP-9 were also lower, possibly because of a lower synthesis of MMP-3." (PMID 25932044, 2015). "To further confirm the relationship by which PP4C promote tumor growth and metastasis via upregulation of MMP-2 and MMP-9, we evaluated the expression levels of PP4C, MMP-2 and MMP-9 in vivo." (PMID 25927939, 2015). "In vitro and in vivo research has shown that MMP2 over-expression is necessary for tumor invasion and that MMP2 and MMP9 promote tumoral cell colony formation." (PMID 26082904, 2015). "Accordingly, a correlation between tumour MMP-9 expression and preoperative serum levels of MMP-9 has been observed in individuals with CRC17." (PMID 26264519, 2015). "This study was designed to investigate the expression of tumor MMP-9 in operable NSCLC and to analyze the relationship between tumor MMP-9 expression and prognosis." (PMID 25888323, 2015).
tumor (continued). "Accordingly, inhibition of COX-2 prior or during PDT with NSAIDs decreased tumor cell survival in a variety of (tumor) cell lines, which coincided with a reduction in levels of PGE2 and the proangiogenic factors MMP9, TNF-α, IL-1β, IL-10, and VEGF." (PMID 26516076, 2015). "Src-FAK signaling has been recently reported to promote E-cadherin internalization, which facilitates tumor cell motility, inhibits the endocytic pathway, and activates MMP2 and MMP9 during cancer progression." (PMID 25969668, 2015). "It has been also reported that overexpression of c-Jun induces expression of MMP-9 and ECM invasion in tumor cells." (PMID 26581505, 2015). "EGFR activation in human carcinoma cell lines also increases matrix metalloproteinase-9 (MMP-9) activity, which increases in vitro cell invasion by facilitating disintegration of ECM barriers to tumor invasion." (PMID 26635612, 2015). "We observed a statistically significant correlation between MMP-9, VEGF expression, and tumor grading (P = 0.003 and P = 0.001)." (PMID 25821815, 2015). "Significant differences in GS were identified in relation to the expression profiles of ITGAV1, ITGA3, ITGA6, SPARC, MMP9, and MMP16, markers that were detected in the tumour samples examined." (PMID 26674523, 2015). "a2NTD treatment promotes the mRNA expression of protumorigenic factors correlated with tumor angiogenesis and metastasis; IL-8 (7.98-fold), VEGF (2.2-fold) and MMP-9 (1.87-fold) as compared with PBS-treated neutrophils." (PMID 26460736, 2015). "CHI3L1-positive tumor cells, exhibiting altered regulation of VEGF and MMP9, decreased expression of cadherin and increased cell motility, display the combination of characteristics required to generate metastases as CTCs." (PMID 26425658, 2015). "The screening analysis by Proteome Profiler showed distinctly altered expression of sE-cadherin, E-selectin, MMP2, MMP9, TIMP1, TIMP2, Galectin and Clusterin in the serum of tumor patients compared to controls." (PMID 25967040, 2015). "In BCYW, univariate analysis identified tumor size, LNM, TNM stage, and MMP-9 expression levels to be adverse prognostic factors for OS and DFS (P<0.05 for each factor)." (PMID 26656588, 2015). "Similar antiangiogenic effects of adiponectin have been studied in tumour growth suppression involving Rho kinase/IFN-inducible protein 10 and matrix metalloproteinase 9 (MMP-9)." (PMID 25650072, 2015). "IHC staining reaction of the tumor was present in 44-60 % for MMP2, MMP7, and MMP9, as well as in 96 % and 80 % for mTOR and p-mTOR, respectively." (PMID 26652716, 2015). "Selective P2X7 antagonist, oATP, inhibited tumor angiogenesis via suppression of MMP-2, MMP-9, and VEGF." (PMID 25933224, 2015). "Quantitation of transcript levels in cultured tumor cells demonstrated that isoproterenol upregulated MMP2 and MMP9 expression by two-fold and four-fold, respectively, with the endogenous catecholamine norepinephrine shown to have similar effects." (PMID 26193320, 2015). "Tumor MMP-9 expression, age, LVI, tumor histology, and tumor stage were tested as independent possible prognostic variables." (PMID 25888323, 2015). "Tumoral grade, tumoral stage, lymphatic metastasis and history of smoking were significantly related to MMP2 and MMP9 expression." (PMID 26082904, 2015). "The impact of BASIGIN on MMPs production by tumour cell lines was first evaluated by analysing the MMP2 and MMP9 activities in CM from wt versus BSG−/− tumour cell lines alone, or co-cultured with fibroblasts." (PMID 26284589, 2015). "It has been demonstrated that N-BPs decrease MMP-9 secretion by breast tumour-bearing mice (the FVB x BALB-neuT model), thereby decreasing tumour infiltration by macrophages." (PMID 25588705, 2015). "The expression levels of AR, MMP-2 and MMP-9 in HCC tissues and tissues adjacent to the tumor were measured by immunohistochemical staining assay." (PMID 25667651, 2015).
tumor (continued). "Tumor cells degrade and remodel the extracellular matrix (ECM) by excessively secreting matrix metalloproteinases (MMPs) such as MMP-2 and MMP-9." (PMID 26170886, 2015). "After incubation for 10 hours, the cells were harvested and the supernatant assayed for secreted Matrix Metalloproteinase 9 (MMP-9), a key enzyme in extracellular matrix remodeling and tumor progression." (PMID 25774696, 2015). "It was also noticed that the development of tumor growth by SaOS2 cells on CAM is majorly depends on the activation of VEGF165, MMP2 and MMP9 and is in concordance with other animal model studies." (PMID 26109911, 2015). "FAK overexpression occurs early in HNSCC development, correlating with increased tumor cell invasion and lymph node metastasis, partially through an increase in MMP-2 and MMP-9 secretion." (PMID 25734659, 2015). "MMP-9 digests type IV collagen, which is the primary component of ECM, and has been shown to play a substantial role in tumor invasion and metastasis." (PMID 26429875, 2015). "MMP2 and MMP9 are over-expressed in the invadopodia at the leading edge of tumours, but also when MMP2 is expressed in the surrounding stroma or MMP9 at pre-metastatic sites they can exert pro-metastatic activity." (PMID 26513020, 2015). "MMP9, which belongs to the ECM-degrading enzyme family, is involved in migration and invasion of tumor cells." (PMID 26194347, 2015). "Immunohistochemical analysis showed BEL decreased nicotine-induced MMP-9, HIF-1alpha, and CD31 tumor tissue expression." (PMID 26588686, 2015). "However, 28 days after treatment there was an increase in angiostatin followed by increase of the tumor size and decreased in MMP-9 level, indicating development of resistance to the treatment and suggesting that angiostatin might have acted in a compensatory role." (PMID 25549350, 2014). "It is also apparent that gelatinase B/MMP-9 plays important tumour suppressing functions, producing endogenous angiogenesis inhibitors, promoting inflammatory anti-tumour activity, and inducing apoptosis." (PMID 24473089, 2014). "Immunostaining of MMP9 and MMP14 in the tumor tissues were both inversely correlated with miR-34a expression measured by qRT-PCR." (PMID 25268950, 2014). "MMPs, especially MMP-2 and MMP-9, as well as their endogenous inhibitors (TIMPs, especially TIMP1) are known to be important in tumor development, tumor cell invasion and metastasis." (PMID 24959847, 2014). "Adiponectin inhibited not only MMP-9 expression but also the ROCK/IP10/VEGF signaling pathway, resulting in suppression of tumor angiogenesis and cell migration." (PMID 24978432, 2014). "To localize MMP-9 expression in PTC and corresponding non-tumor tissue, we used two commercial antibodies that recognize either both pro-active and active or only active form of MMP-9 for immunohistochemistry." (PMID 24778099, 2014). "DTCs were detected using immunocytochemistry, the level of tumor hypoxia using NMR spectroscopy, CD68, CD34, VEGF, and VEGFR-1 (Flt-1) expression using immunohistochemistry, and MMP-2 and MMP-9 activity using zymography." (PMID 24669218, 2014). "Inhibition of IL-17 significantly suppressed CD31, MMP9 and VEGF expression in tumor tissue and inhibited tumor growth." (PMID 25489847, 2014). "Our data identifies MMP9 as a novel WT1 target gene and demonstrates that WT1 expression directly regulates tumor growth through a global effect on angiogenesis." (PMID 24810959, 2014). "Some MMPs, like MMP-2, MMP-9, and MMP-14, can act both as positive and negative regulators of angiogenesis in tumor vasculature." (PMID 24578639, 2014). "Molecular studies done on excised tumor (A549) tissue suggested that BBR in SD form resulted in a significant decrease in the survivin, Bcl-2, cyclin D1, MMP-9, HIF-1α, VEGF and CD31 expressions." (PMID 24614362, 2014). "A number of studies revealed positive correlations between tumor invasion and the activities of the gelatinases MMP-2 and MMP-9." (PMID 25097794, 2014).
tumor (continued). "It turns out that MMPs play a crucial role in the tumor growth, invasion, metastasis, and angiogenesis in cancer tissue, in which gelatinase (MMP-2, MMP-9) is closely related to malignant tumors." (PMID 24971318, 2014). "In a mouse model for cervical cancer, inhibition of MMP-9 in macrophages blocked the release of VEGF and thereby inhibited angiogenesis and tumor growth." (PMID 24578639, 2014). "MMP-2, MMP-9 and uPA act as pivotal roles in degrading ECM and are involved in tumor metastasis and invasion." (PMID 25222667, 2014). "The difficulty will be to inhibit the tumour promoting functions of gelatinase B/MMP-9, whilst substituting for anti-tumor gelatinase B/MMP-9 effects and minimising the inhibition of physiological gelatinase B/MMP-9 function." (PMID 24473089, 2014). "CD147, designated as extracellular MMP inducer (EMMPRIN), is overexpressed in tumor cells and is capable of stimulating the production of various MMPs such as MMP-1, MMP-2, MMP-3, MMP-9, and MMP-11." (PMID 24996644, 2014). "Bands corresponding to latent MMP-9 and MMP-2 were clearly detected in all tumor samples, whereas active forms of MMP-9 and MMP-2 showed less distinct bands or no bands in some samples." (PMID 24778099, 2014). "curcumin has been shown to suppress the expression of a variety of NF-κB regulated gene products involved in carcinogenesis and tumor growth including cyclin D1, VEGF, COX-2, c-myc, Bcl-2, ICAM-1 and MMP-9." (PMID 25866478, 2014). "Peptide mimics of the first and fourth blades of the gelatinase B/MMP-9 hemopexin domain block gelatinase B/MMP-9 dimerization and inhibit HT-1080 and MDA-MB-435 tumour cell motility." (PMID 24473089, 2014). "Furthermore, we observed a decrease in the MMP-9 protein level, a cell migration regulator in gliomagenesis, in cells with elevated miR-503 compared to control samples as shown by western blot assays, suggesting a potential mechanism of miR-503 inhibiting tumor invasion." (PMID 24378652, 2014). "Immunohistochemical analyses revealed that MMP-9, MMP-2, and uPA expression levels were markedly reduced after all treatments in both in vivo tumor models." (PMID 24900952, 2014). "Considering the role of MMP9 and other members of MMP family in mediating invasion of tumor cells, inhibition of mRNA expression for MMP9 following depletion of CIP2A clearly indicated a direct effect of CIP2A in metastasis in this cancer." (PMID 25015035, 2014). "We also review tumour-associated mechanisms that alter the equilibrium between gelatinase B/MMP-9 and its inhibitors and address novel ways to inhibit gelatinase B/MMP-9 involvement in tumour progression." (PMID 24473089, 2014). "In tumor cells, EMMPRIN promotes the production of MMP-1, MMP-2, and MMP-9 and facilitates the synthesis of MT1-MMP and MT2-MMP." (PMID 24705283, 2014). "Taken together, our data suggest that MMP9-induced HSPB1 cleavage acts to regulate the activity of -tumor vascular ECs, releasing anti-angiogenic C-terminal fragment against tumor progression." (PMID 24465581, 2014). "In this study, we demonstrate that HSPB1 processing by MMP9 releases anti-angiogenic fragments of HSPB1 and this cleavage acts to maintain the angiogenic balance in tumor progression." (PMID 24465581, 2014). "Potential pro-oncogenic roles for gelatinase B/MMP-9 have been reported, implicating gelatinase B/MMP-9 in neoplastic transformation, tumour initiation/promotion and genetic instability." (PMID 24473089, 2014). "Studies on the SUM149 IBC cell line actually demonstrated that the invasive nature of IBC tumour cells critically depends on the overexpression of functional E-Cadherin and the influence thereof on MMP1 and MMP9 expression." (PMID 24586640, 2014). "Among the studied genes, the overexpression of the following metalloproteinases in the tumor tissue can be correlated to at least one clinicopathological variable: MMP-1, MMP-2, MMP-9, MMP-11, and MMP-16." (PMID 24737953, 2014).